RUNX3 (RUNX family transcription factor 3)
Diseases named in the same sentence as RUNX3 in open-access papers (continued):
Sharing a sentence is not in itself a finding about the gene and the disease.
gastric cancer (continued). "The CpG island of the RUNX3 gene is frequently hypermethylated in gastric cancer." (PMID 16827945, 2006). "We ascertained differences in the potential of gastric carcinogenesis between the anastomotic site and other areas in the remnant stomach after distal gastrectomy for peptic ulcer (RB group) or gastric cancer (RM group), by analysing RUNX3 with special reference to topography." (PMID 15685235, 2005). "RUNX3 is one of the genes with RUNT domain, which has been identified to have a tumor suppressor role that frequently shows loss of expression due to hemizygous deletion and hypermethylation in gastric cancers." (PMID 15574200, 2004). "We investigated whether RUNX3 upregulates WNT5A in other gastric cancer cell lines." (PMID 38240752, 2024). "In addition, the induction of cytoplasmic RUNX3 retention under hypoxic culture condition in gastric cancer cells occurs via the upregulation of histone deacetylase (HDAC) and histone methyltransferase (HMT), euchromatic histone-lysine N-methyltransferase 2 (EHMT2/G9a)." (PMID 38683453, 2024). "Additionally, re-expression of RUNX3 in gastric cells in a mouse model inhibited peritoneal metastasis and RUNX3 restoration in human gastric cancer cells suppressed vascular endothelial growth factor A (VEGF A) expression, leading to inhibition of angiogenesis, growth, and metastasis." (PMID 33298014, 2020). "Because this study suggests that the serum DNA testing of methylated RUNX3 by the CORD assay may be useful to detect individuals with early gastric cancer, confirmatory studies using independent data sets with larger sample sizes will be needed to support our findings." (PMID 32224873, 2020). "Furthermore, EZH2 is known to down-regulate the expression of RUNX3 in gastric cancers." (PMID 32943993, 2020). "The combined genotype such as ITGA5-1160/ITGB1-1949/ITGB1 + 31804 as T/A/C carriers and COX-2-1195/IL-10-592 as G-carrier/AA, or even more specifically combined with RUNX3 + 492/TFF2-308, may thus serve as a host factor to identify the risk group of gastric cancer for an early H. pylori eradication." (PMID 25884934, 2015). "Thus, RUNX3 suppressed gastric cancer cell invasion and vimentin expression by activating miR-30a." (PMID 24447545, 2014). "Here, we investigated whether RUNX3 regulates the EMT in gastric cancer cells." (PMID 24447545, 2014). "In the present study, we investigated the correlation between Hlx and T-bet or IFN-γ as well as the expression level of Runx3 in patients with gastric cancer in order to determine whether Hlx contribute to the pathological event leading to the imbalance of Th1/Th2 in gastric cancer." (PMID 23243425, 2012). "The aggregated results found that RUNX3 methylation was more frequent in intestinal-type compared with diffuse-type gastric carcinomas, suggesting that inactivation of RUNX3 might play a more significant role in the development of intestinal-type gastric carcinomas." (PMID 21867527, 2011). "A study showed in gastric cancer, YAP binds to RUNX3 instead of TEAD, the binding protein required for transcription in the nucleus, thereby reducing the tumorigenicity of MKN28 gastric cancer cells." (PMID 38925618, 2024). "We next examine the coexpression of RUNX3 and WNT5A in E-cadherin positive gastric cancer cells in the human specimens (n = 35)." (PMID 38240752, 2024). "In human gastric cancer, suppressing MEX3B expression inhibits the ubiquitylation and degradation of RUNX3, while the interaction of lncRNA HOTAIR with RUNX3 promotes the MEX3B-dependent ubiquitylation and degradation of RUNX3." (PMID 38424632, 2024).
gastric cancer (continued). "In particular, RUNX3 binds to the WNT5A gene and is required for strong WNT5A expression in the gastric cancer cell line HGC-27." (PMID 38240752, 2024). "Intriguingly, in certain gastric cancer cell lines such as KatoIII and SNU668, RUNX3 paradoxically elevated Wnt signaling activity, implying a cell-context-dependent role for RUNX3." (PMID 38430423, 2024). "In gastric cancer cells, the histone methyltransferase (HMT) G9a methylates lysines of the Runt domain of RUNX3 (K129 and K171) to promote nuclear export and cytoplasmic degradation." (PMID 36899853, 2023). "It is also interesting to note that under hypoxia, RUNX3 is silenced by G9a-mediated histone methylation and HDAC-mediated histone deacetylation on the promoters of Runx3 in gastric cancer cells." (PMID 36899853, 2023). "RUNX3 expression is negatively correlated with VEGF expression and microvascular density in the tissues, suggesting its anti-angiogenic role in human gastric cancers." (PMID 36231060, 2022). "RUNX3 suppresses cancer growth by interacting with the TEAD–YAP complex and inhibiting its transcriptional activity in gastric cancer cell lines." (PMID 34831147, 2021). "RUNX3 methylation analysis by serum CORD assay showed moderate sensitivity and moderately high specificity for the detection of early gastric cancer." (PMID 32224873, 2020). "In gastric cancer cells, TGF-β-driven RUNX3 antagonized WNT-signaling via a RUNX3/TCF4/β-catenin complex, which in our model would result in suppression of hypertrophy." (PMID 32195247, 2020). "In conclusion, the RUNX3 methylation analysis by serum CORD assay showed moderate sensitivity and moderately high specificity for the detection of early gastric cancer." (PMID 32224873, 2020). "miR-148a modulates the expression of runt-related transcription factor 3 (RUNX3), an important tumor suppressor, through inhibition of DNMT1-dependent DNA methylation in gastric cancer." (PMID 29721215, 2018). "In gastric cancer, methylation status of one or more individual CpG sites in genes DACT1, PAX5, and RUNX3 promoter region was also applicable for prognosis." (PMID 29610526, 2018). "Recently, RUNX3 has been reported to attenuate Wnt signaling by directly suppressing β-catenin/TCF4 in colon cancer and gastric cancer." (PMID 27825140, 2017). "The Runt-related transcription factor 3 (RUNX3) gene is a tumor suppressor in many tissues and often inactive in gastric cancer." (PMID 28512631, 2017). "RUNX3 regulates gastric cancer cell proliferation via the TGF-β and Wnt pathways and affects angiogenesis in gastric cancer by regulating the expression of vascular endothelial growth factor (VEGF)." (PMID 27464701, 2016). "Decreased RUNX3 expression directly downregulates miR-30a expression, which enhances the expression of the miR-30a target gene vimentin and promotes EMT in gastric cancer cells." (PMID 27464701, 2016). "miR-130a directly targeted runt-related transcription factor 3 (RUNX3) and promoted gastric cancer tumorigenesis by targeting RUNX3." (PMID 26134263, 2015). "Thus, miR-130a may act as an oncogene in gastric cancer by targeting RUNX3." (PMID 26134263, 2015). "We found that the gastric cancer cell migration, invasion and proliferation were completely restored in the AGS cell line with a forced miR-130a expression and RUNX3 restoration." (PMID 26134263, 2015). "Knockdown of RUNX3 promoted the EMT and increased the protein expression of the mesenchymal marker vimentin in human gastric cancer cells." (PMID 24447545, 2014). "Therefore, we addressed whether RUNX3 has a role in the EMT in gastric cancer." (PMID 24447545, 2014). "Whereas in gastric cancer cells ATBF1 is located in the cytoplasm and can be tanslocated into the nucleus with RUNX3 upon TGFβ activation, we found that ectopically expressed ATBF1 is localized in the nucleus in 22Rv1 prostate cancer cells as in normal cells." (PMID 24651376, 2014).
gastric cancer (continued). "In gastric cancer, a large number of genes (e.g., CDKN2A, CDK2AP2, CDH1, MGMT, RASSF1, RUNX3, and DLC1) have been shown to be suppressed by CpG island hypermethylation." (PMID 23179365, 2013). "In this study, the Hlx, T-bet, Runx3, and IFN-γ were measured in PBMC from patients with gastric cancer and the correlation between Hlx and T-bet or IFN-γ was assessed." (PMID 23243425, 2012). "Runt-related transcription factor 3 (RUNX3) is a member of the runt-domain family of transcription factors and has been reported to be a candidate tumor suppressor in gastric cancer." (PMID 21867527, 2011). "Runt-related transcription factor 3 (RUNX3), located on chromosome 1p36, is correlated with tumorigenesis and gastric cancer progression." (PMID 21205319, 2011). "RUNX3 mRNA expression was also examined in various cancer cell lines including colon cancer (RKO and HCT116), gastric cancer (MKN-1 and MKN-45), leukemia (HL60), lymphoma (U937) and breast cancer (MCF7 and SK-BR3)." (PMID 19521519, 2009). "For example, 45%–60% of human gastric cancers do not express RUNX3 due to hemizygous deletion and hypermethylation of the RUNX3 promotor, and Runx3 knock-out mice develop hyperplasia of the gastric mucosa." (PMID 39843653, 2025). "For RUNX3, a tumor suppressor role has been reported in gastric cancer, contingently via a mechanism involving negative regulation of MMP9 and vimentin." (PMID 38630262, 2024). "Not surprisingly, 60% of patients with gastric cancer do not express RUNX3 due to hemizygous deletion and hypermethylation of promoter region." (PMID 38240752, 2024). "As for the remaining population of patients with gastric cancer with high RUNX3 expression, the role of RUNX3 has not been examined." (PMID 38240752, 2024). "Forty-five percent to 60% of patients with gastric cancer do not express RUNX3 due to hemizygous deletion and hypermethylation of promoter region." (PMID 38240752, 2024). "In cases of gastric cancer, however, the absence of RUNX3 accelerates the progression toward peritoneal metastasis." (PMID 38430423, 2024). "The positive correlation between RUNX3 and WNT5A expression could therefore be commonly observed in gastric cancer." (PMID 38240752, 2024). "ATBF1 nuclear localization was significantly correlated with runt domain transcription factor 3 (RUNX3) in gastric cancer tissue samples, and ATBF1 was transferred from the cytoplasm to the nucleus under TGF-β treatment in SNU16 gastric cancer cells, which was also detected in HaCaT cells." (PMID 36476423, 2022). "This transcriptional regulation decreased mRNA level of RUNX3 as well as the protein level in several gastric cancer cell lines, however, not in all tested." (PMID 33116296, 2021). "Protein levels of G9a were increased under hypoxia, while protein levels of RUNX3 were decreased under hypoxia in the gastric cancer cell lines without affecting mRNA levels of RUNX3." (PMID 33116296, 2021). "Because this study suggests that the serum DNA testing of methylated RUNX3 by the CORD assay may be useful in detecting gastric cancer, the CORD assay may provide an alternative screening strategy to detect even early-stage gastric cancer." (PMID 32224873, 2020). "Induction of only RUNX3 at unaffected RUNX2 was observed after BMP stimulation of the human gastric cancer cell line HT-29, corroborating the non-redundant regulation of RUNX2 and RUNX3 expression by BMP signaling." (PMID 32195247, 2020). "Similarly, miR-106a promoted chemoresistance of gastric cancer cells and suppressed drug-induced apoptosis through targeting RUNX3 (runt related transcription factor 3)." (PMID 25760076, 2015). "There were two additional SNPs being included, with the runt-related transcription factor 3 gene (RUNX3) related to SPEM formation and intestinal-type gastric cancer, and the trefoil factor 2 (TFF2) gene expressed in SPEM during H. pylori-related gastric carcinogenesis." (PMID 25884934, 2015).
gastric cancer (continued). "Additionally, Runx1 and Runx3 proteins have been shown to regulate the PI3K/Akt pathway in megakaryocytic leukemic and gastric cancer cell lines by directly affecting expression levels of p110 and Akt1 proteins, respectively." (PMID 24479521, 2014). "In this study, we addressed whether RUNX3 has a role in the EMT, related to cancer relapse and metastasis, in gastric cancer." (PMID 24447545, 2014). "A highly significant negative correlation between RUNX3 and vimentin protein was observed in these gastric cancer samples (P < 0.0001)." (PMID 24447545, 2014). "The addition of MG132 did not abolish the ability of ectopically expressed RUNX3 to decrease vimentin protein level in gastric cancer cells." (PMID 24447545, 2014). "Other studies of individual genes also support this conclusion, for example, RUNX3 is frequently hypermethylated in gastric cancers but is never expressed in normal gastric epithelia." (PMID 23034185, 2012). "RUNX3 is one of Runt-related (RUNX) gene family members and has been considered to be a candidate tumor suppressor for human gastric cancer, however, it remains unclear how RUNX3 exerts its tumor suppressor function." (PMID 24212651, 2011). "As endoscopic resection is applied to the treatment of early gastric cancer without lymph node metastasis, the serum circulating methylated RUNX3 copies could be a biomarker to determine whether early gastric cancer is resected endoscopically or surgically." (PMID 32224873, 2020). "Numerous studies suggested that promoter methylationof the RUNX3, RASSF1A and Reprimo genes was more common in GC tissues compared with normal tissues, suggesting that promoter methylation of the RUNX3, RASSF1A, and Reprimo genes may induce the tumorigenesis of gastric cancer." (PMID 29100425, 2017). "RASSF1A, p14ARF, and MGMT; CHRNA3, DOK1, and GNMT; p16, hMLH1, MINT1, MINT2, MINT12, MINT25, and MINT31; APC, CDH1, MHL1, CDKN2A, CDKN2B, and RUNX3; CDH1; DKK3; PTEN; MGMT; TFPI2; CACNA2D3; PCDH10; SOX2; MAL; and COX2 were previously reported to be hypermethylated in gastric cancer." (PMID 26121593, 2015). "This suggests that RUNX3 methylation was not correlated with age in gastric cancer tissue." (PMID 21867527, 2011). "Thus, an increase in the number of methylated RUNX3 copies in blood may suggest the presence of some kind of cancer or benign disease, not just that limited to gastric cancer." (PMID 32224873, 2020). "However, in our study, RUNX3 did not induce E-cadherin in human gastric cancer cells." (PMID 24447545, 2014). "However, in specific gastric cancer cells such as SNU5 and SNU484 cells, RUNX3 mRNA expression was not decreased, but its protein level was reduced under hypoxic conditions." (PMID 26375442, 2015). "To confirm whether miR-130a promotes gastric cancer migration, invasion and proliferation by targeting RUNX3, we forced the expression of miR-130a in AGS and MKN45 cell lines along with a construct containing the RUNX3 coding sequence but lacking the 3′UTR of the RUNX3 mRNA." (PMID 26134263, 2015).
breast carcinoma (76 papers, 2007 to 2025). "Previously, aberrant epigenetic modifications have been implicated in breast cancer, highlighting RUNX3 as a promising prognostic biomarker." (PMID 35898303, 2022). "Collectively, this study reveals the underlined epigenetic events responsible for RUNX3-implicated breast cancer metastasis along with the classification of DNMT1 modulators that can potentially drive the perception of epigenetic-based tumor therapy." (PMID 35898303, 2022). "Recurrent mutations in RUNX1 and hyper methylation of RUNX3 locus have recently been discovered in breast cancer indicating tumor suppressor role of RUNX1 and RUNX3." (PMID 29581836, 2018). "RUNX3 is frequently inactivated by hypermethylation in human breast cancers and its haploinsufficiency has been linked with spontaneous breast carcinoma in mice." (PMID 29581836, 2018). "RUNX3 expression is associated with aberrant DNA methylation in adenocarcinoma cells, primary bladder tumor cells, and breast cancer cells." (PMID 25616342, 2015). "Among them, RUNX3 is also a tumor suppressor as it is often inactivatedin human breast cancers and loss of one copy of Runx3 led tospontaneous mammary tumor development in a portion of aged female mice." (PMID 25415051, 2014). "Indeed, RUNX3 gene deletion, polymorphisms and mis-localization of protein have been noted in breast cancers." (PMID 36831308, 2023). "Importantly, increased levels of RUNX3 promoter hypermethylation have been directly linked to increased Erα protein expression in Erα+ breast cancer, implying a potential role of RUNX3 in downregulating Erα protein levels." (PMID 36899853, 2023). "In addition, the early spread of breast cancer is related to the inactivation of RUNX3 gene caused by hypermethylation of promoter and protein mislocation." (PMID 36424557, 2022). "Altogether, these results suggest that the SE-driven abnormal expression of RCAN1.4 mediated by RUNX3 loss could be physiologically significant and clinically relevant in breast cancer patients." (PMID 32771023, 2020). "RUNX3 overexpression is associated with decreased breast cancer cell invasiveness." (PMID 32765634, 2020). "Thus, RUNX3 could be used as a prognosis marker for breast cancer; stromal RUNX3 expression is positively associated with good outcome." (PMID 37641472, 2023). "RUNX3-regulated pathways appeared in our analysis, consistent with its role as a tumor suppressor frequently downregulated in breast cancer and involved in TGF- signaling." (PMID 40766228, 2025). "In breast cancer, RUNX3 serves as a frequently inactivated or downregulated tumor suppressor that inhibits the proliferative and transformative potential of estrogen receptor α (ERα)-dependent cells, such as the MCF-7 cell line." (PMID 38430423, 2024). "We found that abnormal expression of Runx3 was significantly correlated with prognosis in colorectal cancer, breast cancer and lymphoma." (PMID 37189103, 2023). "Aside from the gastrointestinal tract, RUNX3 is frequently silenced by epigenetic methylation in breast cancer." (PMID 36766749, 2023). "The ability of RUNX3 to modulate ERα activity indicates a strong tumor suppressor role for RUNX3 in breast cancer." (PMID 36766749, 2023). "RUNX3 was part of a poor prognostic stromal gene signature in breast cancer patients, and very recently, RUNX1 (and also RUNX2) was identified through an epigenetic analysis of murine mammary tumors to be highly upregulated in cancer-associated fibroblasts." (PMID 36831308, 2023). "Expression of RUNX3 is inversely correlated with Erα expression in breast cancer cells and human breast cancer samples." (PMID 36899853, 2023). "High expression of Runx3 was related to a favorable prognosis of anti-PD-1 regimen in patients with colorectal cancer, breast cancer and lymphatic cancer." (PMID 37189103, 2023).